MIR4519 (microRNA 4519)
Synonyms: hsa-mir-4519
Gene: MicroRNA gene on chromosome 16 (30,875,266 to 30,875,323, reverse strand). Ensembl gene ENSG00000265991.
Homologues: Orthologues: chimpanzee MIR4519 (100% identical).